CXCL9 (C-X-C motif chemokine ligand 9)
Diseases named in the same sentence as CXCL9 in open-access papers (continued):
Sharing a sentence is not in itself a finding about the gene and the disease.
tumor (continued). "It has been demonstrated that M1 macrophages expressed high levels of CD86, MHC II and B7 and mediated anti-tumor effects by secreting high-level cytokines (such as IL-12, IL-23, IL-1 and IL-6) and chemokines (MCP-1, CCL3, CXCL9, CXCL10, etc.)." (PMID 37762054, 2023). "CXCL9 and CXCL10 through their receptor CXCR3 regulate immune cell migration, differentiation, and activation, leading to tumor suppression under some conditions." (PMID 37296899, 2023). "Several chemokine ligands are expressed by the tumor: CCL17 and CCL22 promote recruitment of CCR4+ Tregs, while CXCR3—along with its ligands, CXCL9 and CXCL10—drives cytotoxic lymphocyte trafficking into the GBM tumor site." (PMID 37443804, 2023). "In this study, we established SCCVII cells stably expressing the IFN-inducible chemokines CXCL9, CXCL10, and CXCL11 and transplanted the cells into the backs of nude mice to investigate their anti-tumor effects." (PMID 37218983, 2023). "Type I and II IFNs are known to induce the production of cytokines, including CXCL9 and CXCL10, which play a role in immune cell migration, differentiation, and activation and ultimately in tumor suppression." (PMID 37478172, 2023). "This recombinant variant was able to drive a substantial increase in the GM-CSF, CXCL9, and TNF-α chemokine gradient between the tumor and blood." (PMID 37112810, 2023). "The secreted CXCL9, CXCL10 and CXCL11 interact with tumour cells to induce cell death, such as apoptosis and attract adaptive immune cells leading to anti‐tumour immunity." (PMID 37170733, 2023). "We specifically showed that IL9-polarized TAMs induced antitumor immunity in mice by recruiting antitumor immune cells into the tumor mass via releasing the macrophage-derived chemoattractants, CCL3/4 and CXCL9/10." (PMID 36968220, 2023). "STING also increases the expression of chemokines, such as CXCL9 and CXCL10, which attract T lymphocytes to tumor tissue, promote tumor cell killing, and initiate adaptive immune responses." (PMID 37719852, 2023). "Since we observed differences in Cxcl9/Cxcl10 staining in KPC2 vs. KPC2a tumors, we next tested if there were tumor cell intrinsic differences in chemokine expression by KPC2 and KPC2a cells." (PMID 36472588, 2023). "In the present study, we constructed cells stably expressing the three IFN-inducible chemokines CXCL9, CXCL10, and CXCL11 in a mouse model and transplanted them into nude mice to investigate their anti-tumor effects." (PMID 37218983, 2023). "When AT-3 tumors were injected into CXCL9/CXCL10 double-knockout hosts or hosts depleted of macrophages, the anti-tumor response of the checkpoint blockade was completely lost." (PMID 38140561, 2023). "CCL5, CCL-11, CXCL9, and CXCL10 are postulated as the main drivers in eosinophil-mediated tumor cell necrosis." (PMID 36427017, 2023). "CXCL9 and CXCL10 produced by myeloid cells in CRC liver metastases induce tumor-infiltrating lymphocytes to invade the margins." (PMID 35935996, 2022). "As an autocrine signal, CXCL9, CXCL10, or CXCL11 activates the chemokines produced by the tumor through CXCR3A on cancer cells and further recruits immune cells to create an immune microenvironment that promotes tumors." (PMID 35992864, 2022). "The chemokine CXCL9, along with its two family members CXCL10 and CXCL11, promotes tumour-suppressive lymphocytic infiltration in solid tumours via its receptor CXCR3." (PMID 35314795, 2022). "We demonstrated overexpression of CXCL9 in mDC_LAMP3 and Macro-2 cells, and overexpression of CXCL10 in proliferating macrophages (Pro Macro) and Macro-2 cells in the tumor." (PMID 36180422, 2022). "Lysate from MTP-treated tumors showed an even stronger upregulation of chemokines involved in immune cell recruitment, including CXCL9, CCL5, CXCL10, CD40 and CXCL16, compared to both control and MTX-treated tumor lysates." (PMID 36397148, 2022).
tumor (continued). "The pro-inflammatory cytokine IFN-γ induces CXCR3 chemokines, e.g., CXCL-9 and CXCL-10, as part of the interferon-stimulated gene cluster that then attracts T cells into the tumor." (PMID 36611932, 2022). "The expression of CXCL9, CXCL10 and CXCL11 is positively correlated with the density of tumor infiltrating NK and T cells." (PMID 35033066, 2022). "To study the functional roles of these T cell-recruiting chemokines, we used neutralizing antibodies to antagonize the expression of CCL5, CXCL9, and CXCL10 in JQ-1-treated tumor-bearing mice." (PMID 35292660, 2022). "Compounds that enhance the expression of CXCL9, CXCL10 or CXCL11 and decrease the expression of CXCR3 on tumor cells have displayed anti-tumor activity." (PMID 35154121, 2022). "Among them, Cxcl9, Cxcl10, and Cxcl11 are most related to the recruitment of CD8+ T cells, as CXCR3, the cognate receptor for CXCL9 and CXCL10, is highly expressed in tumor infiltrated CD8+ T cells." (PMID 35145233, 2022). "The cGAS-STING pathway-induced Type-1 interferon response drives the expression of multiple chemokines such as CXCL9, CXCL10, and CCL5, that act as chemical gradients to direct CTLs into the tumor tissue." (PMID 36353640, 2022). "In high density of LAMP3-DC-mature-type TLS, CXCL9, 10 and 11 are involved in the migration of Th1 cells by binding to the CXCR3 receptor on tumor-infiltrating T cells." (PMID 36704336, 2022). "In summary, we identified SPATA2 and CYLD as novel regulators of T/NK cell-attracting chemokines CXCL9, CXCL10, CXCL11 in tumor cells." (PMID 36531014, 2022). "CXCL9 secretion can be induced by IFN-gamma stimulation, and this IFN-gamma-CXCL9 pathway has an essential role in regulating tumor growth." (PMID 36362062, 2022). "CXCR3, which is expressed on Th1, macrophage and NK cells, and its ligands (CXCL9, CXCL10) is an important chemokine axis in tumor suppression via interferon-induced cell-mediated immunity and inhibition of angiogenesis." (PMID 36132332, 2022). "CXCL9, 10, and 11 and CXCR3 pathways have two modes of action: immune-activated secretory signaling and tumor cell-derived proliferative metastatic signaling." (PMID 36479091, 2022). "Overall, the increased upregulation of CXCL9 and CXCL10, accompanied with the downregulation in CXCL2, may underlie the observed alterations in the cellular components at the level of systemic organs and within the tumor microenvironment following combination treatment." (PMID 36605208, 2022). "DCs were found to elevate the production of CXCL9 and CXCL10 in an IFN-γ-dependent manner, resulting in T cell infiltration to the tumor in many studies." (PMID 35459193, 2022). "cDC1 are the major source of CD8+ T cell chemoattractants CXCL9 and CXCL10; these chemokines drive T cell recruitment and anti-tumor immunity as well as suppress angiogenesis by secretion of anti-angiogenic factor such as IL-12 and IL-18." (PMID 35759090, 2022). "In EBV-positive NPC cells, activated NF-kB regulates a number of chemokines (CXCL9, CXCL10, CX3CL1, and CCL20), which recruit tumor-infiltrating T lymphocytes and modulate the NPC tumor environment." (PMID 36289760, 2022). "Consistent with this, the expression of T cell chemokine genes such as CCL3, CCL4, CCL5, CXCL9, CXCL10 and CXCL1123 in MKN74 tumours tends to be higher than that in other tumours, especially after ERY974 administration." (PMID 36071036, 2022). "In solid tumours, CXCL9, along with the other CXCR3 chemokines, has been made responsible for this tumour-suppressive lymphocytic infiltration." (PMID 35314795, 2022). "The CXCL9,10,11/CXCR3 signaling pathways in the TME mainly facilitate the chemotactic movement of CXCR3-activated immune cells to the tumor site for anti-tumor immunity." (PMID 36479091, 2022).
tumor (continued). "In melanoma and breast cancer cells, hypoxia induces HIF-dependent expression of BIRC2, which inhibits expression of CXCL9, thereby blocking recruitment of NK and CD8+ T cells to the tumor, leading to increased tumor growth and resistance to anti–PD-1 therapy." (PMID 35642641, 2022). "Recent discoveries reveal several mechanisms, such as epigenetic silencing of CCL5, CXCL9, and CXCL10 in different tumor entities or post-translational cleavage of those same chemokines by enzymes such as dipeptidylpeptidase 4 or matrix metalloprotease-9." (PMID 36366354, 2022). "Decreased expression of CXCL9 and CXCL10 renders EOC cells resistant to anti-tumor T-cell infiltration and eventually leads to immune escape." (PMID 35269786, 2022). "The M1-polarized TAMs secrete CXCL9 to serve as a chemoattractant to Trm through its CXCR3 receptors and they elevate their update of unique fatty acids from the tumor microenvironment that are required for the survival and maintenance of Trm31." (PMID 36050391, 2022). "CXCL9 and CXCL11 recruit CXCR3+ T cells to the skin and overexpressed in rashes, higher CXCL9 and CXCL11 expression in macrophages had more CD8+ T cells in the tumor microenvironment." (PMID 36479091, 2022). "Among them, two vital chemokines (CXCL9 and CXCL10), which trigger the recruitment of CD8+ T cells into the tumor microenvironment (TME) in BLCA, were upregulated in the high-GNG4 group." (PMID 35456499, 2022). "In view of their ability to promote effector T cell differentiation, CXCL9 (and CXCL10) are investigated as effector molecules for enhancing anti-tumor immunity and restraining tumor growth." (PMID 35967369, 2022). "The CTSB on tumor cells surface can remove the autoreactive lymphocytes and degrade these cytotoxic effector molecules (such as IgG and chemokines CXCR3, CXCL9, CXCL10) synthesized from tumor-suppressive infiltrating immune cells." (PMID 35277559, 2022). "The downstream target TIL then collects chemokine genes CXCL9, CXCL10, CXCL11, and CD8 + T cell activation markers, all of which contribute to a successful anti-tumor immune response." (PMID 36071479, 2022). "CXCL9, 10, and 11 are ELR-negative CXC chemokines that can exert an inhibitory effect on tumor growth by inhibiting angiogenesis and thus tumor growth." (PMID 36479091, 2022). "Anti-CXCR3 treatment completely abrogated the attenuated tumor growth observed in GPR182−/− mice, suggesting that the improved anti-tumor immunity seen in GPR182−/− mice is dependent on the CXCL9/CXCL10/CXCR3 axis." (PMID 35013216, 2022). "In mice, IFN-γ promoted CXCR3 expression on NK cells and also enhanced the production of its ligands, CXCL9 and CXCL10, on virus-infected cells and tumor cells;183,255 these ligands are important for NK cells’ anti-infection and anti-tumor properties." (PMID 35768424, 2022). "Chemokines, such as CXCL9 and CXCL10, serve as key factors that recruit Teffs into the center of the tumor, further promoting antitumor immunity and disrupting tumor cell proliferation and invasion." (PMID 35488336, 2022). "Cyclin G2 is upregulated by IFN-γ in macrophages, promotes the secretion of CXCL9 to increase CTL chemotaxis and inhibit angiogenesis to suppress tumor growth." (PMID 36566226, 2022). "IFN-γ promotes the infiltration of the tumor with leukocytes, including CD8 T cells, by driving the secretion of CXCL9 and CXCL10." (PMID 35103755, 2022). "To further investigate changes in the tumor microenvironment, we determined the levels of TAM‐produced cyto/chemokines Ccl2, Ifnγ, Cxcl10, Cxcl9, Csf1, Csf3, and Il‐6 in the peritoneal lavage." (PMID 36221913, 2022). "For instance, DCs secrete CXCL9 and CXCL10 as chemoattractors for recruiting CXCR3+ T cells into the tumor microenvironment." (PMID 35347124, 2022).
tumor (continued). "We found that the protein levels of CXCL9 and CXCL10 were obviously elevated, and the protein level of caveolin-1 was downregulated in the tumor cells of mice treated with anti-GD2 mAb plus MβCD compared with the other three groups." (PMID 36284313, 2022). "While CXCL9 upregulates and recruits immune cells in the TME to inhibit tumor growth, it also induces PD-L1 expression to help tumors escape immune cell surveillance." (PMID 36362062, 2022). "Romidepsin induced the secretion of various chemokines from tumor cells, such as CCL5, CXCL9 and CXCL 10, attracting T lymphocytes into the tumor." (PMID 36080223, 2022). "Drugs that enhance the expression of paracrine CXCL9, ‐10, and ‐11 and inactivate CXCR3 expression on cancer cells have exhibited antitumor activity in several tumor models." (PMID 35702353, 2022). "Our study firstly revealed the positive correlations between NLRC3 and CCL5 and CXCL9 expressions in HCC, which explained the mechanisms of NLRC3-related CD8+ T cell infiltration in tumor." (PMID 35145917, 2022). "Recently, CXCL9 and CXCL10 were reported to be necessary for the trafficking of activated CD8+ T cells into tumor sites." (PMID 36284313, 2022). "It has been reported that IFN-γ-related gene expression contributes to immunotherapy prediction, such as CCR5, CXCL9, IFNG, STAT1, and PRF1, and these genes are related to tumor antigen presentation, T cytotoxic activity, and immune cell infiltration." (PMID 35432443, 2022). "Previous studies have revealed that the Th1 chemokines CXCL9 and CXCL10 enhance the tumor attack of effector T cells and increase PD-L1 blockade." (PMID 35531878, 2022). "In lung and renal cell carcinoma models, intratumoral injection of CXCL9 or CXCL10 proteins, respectively, reduced neovascularization and delayed tumor growth by inducing tumor‐infiltrating CXCR3+ monocytes." (PMID 35702353, 2022). "In the literature, it is described that the CXCR3/CXCL9/CXCL10 signaling axis modulates the proliferation, migration and survival of tumor and endothelial cells." (PMID 35897689, 2022). "In response to Alb-IFNβ, we observed an upregulation in CXCL9 and CXCL10 expressions in the tdLNs, which are chemoattractants secreted by DCs to recruit T cells to the tumor." (PMID 35459734, 2022). "Results of qRT-PCR partially demonstrated the bioinformatics results that the mRNA levels of CXCL10, CXCL9, CCL5, and CCR2 were remarkably elevated in tumor tissues collected from PTC patients coexistent with HT than those without HT." (PMID 36266640, 2022). "Cooperation between PRC2 and DNMT1-mediated DNA methylation was shown to suppress the expression of T helper 1 (Th1)-type chemokines CXCL9 and CXCL10 to impede tumor infiltration of CD8+ T cells." (PMID 36323669, 2022). "IFNγ receptor signaling leads to an increase in the production of CXCR3 ligands, namely CXCL9, 10 and 11 which have the potential to promote the avidity of LFA-1 on T cells as well as to attract other immune effector cells to the tumor site." (PMID 36189315, 2022). "At the same time, it was also confirmed that NLRC3 was positively correlated with CXCL9 (P<0.0001, R2 = 0.2338) expressions in HCC tumor." (PMID 35145917, 2022). "CXCL9, an IFN-γ inducible chemokine, has been reported to play versatile roles in the tumor-host relationship." (PMID 35392957, 2022). "Phosphorylated ATM was identified as a driving factor of cytokine production that can increase tumor cell-derived levels of CCL5, CXCL9, CXCL10, and IL16, leading to increased CD8+ CTL infiltration." (PMID 36071479, 2022). "CXCL9, CXCL10, and CXCL11/CXCR3 axes can induce immune activation and then inhibit tumor growth, which are potential novel therapeutic targets for cancer therapy." (PMID 36090326, 2022). "To further explore the effect of anti-GD2 mAb plus MβCD on tumor immunity, we detected the protein expression of CD8A, caveolin-1, CXCL9, and CXCL10 by IHC staining." (PMID 36284313, 2022).
tumor (continued). "Neutralizing CXCL9, CXCL10, or IFN-γ reduces CXCR3-expressing activated T cells infiltrating tumors and abrogates IL-7/IL-7rα-Fc-mediated tumor growth inhibition." (PMID 36479091, 2022). "Emerging data suggests that enrichment in tumor-infiltrating CD8 + T cells and expression of immune genes such as IFN-γ, CXCL9, and CXCL10 is an indicator for immunotherapy response." (PMID 35027623, 2022). "Besides, CCL5, CCL19 and CXCL9 were positively correlated with CD8+ T cell infiltration assessed by QUANTISEQ (Rho = 0.818, 0.578, and 0.716, respectively), which suggested that a high expression of CCL5, CCL19, and CXCL9 might promote the tumor infiltration of CD8+ T cells in CL-BCa." (PMID 35359417, 2022). "A recent immunohistochemistry and RNA-sequencing meta-analysis of resectable and advanced PDAC specimens showed a positive correlation between CCL5, CXCL9 and CXCL10 and CD8+ T cells infiltration in close proximity to tumor cells." (PMID 35954489, 2022). "The chemokine CXC motif receptor 3 (CXCR3), the CXCL9, CXCL10 and CXCL11 specific receptor, participates in the tumor migration, invasion, angiogenesis and immunity and are mainly expressed on monocytes, effector T cells, NK lymphocytes and cancer cells." (PMID 36030223, 2022). "DNMT1 suppresses tumor production of CXCL9 and CXCL10 and subsequently reduces T-cell tumor migration." (PMID 34385592, 2022). "CDH17 ‘high-methylation’ cases, showed increased expression of IL12B, IL10, CXCL9 and 10 and CCL2 compared to CDH17 ‘low-methylation’ cases, suggestive of a favourable cytokine/chemokine ‘milieu’ in these tumours." (PMID 36612154, 2022). "Patients that respond to PD-1 blockade also exhibited increased expression of STAT1, CXCL9, CXCL10, GZMB, CD8A, and CD8B, which is consistent with our observation in tumor model with IFNα-MSC treatment." (PMID 35145233, 2022). "IFN-γ-inducible CXCL9, CXCL10, and CXCL11 are chemokines attracting cytotoxic T cells to infiltrate into tumor tissues and exert anti-tumor effects." (PMID 35300424, 2022). "A mouse model revealed the importance of eosinophils in improving the infiltration of CD8+ T cells into the tumor by CCL5, CXCL9 and CXCL10 production, thus referring to their active participation in tumor rejection." (PMID 35565423, 2022). "An observation in OPSCC demonstrated that intra-epithelial B cells interacted with T cells via CXCL9 in the TME, while tumor killing capability of B cells was induced by IL-17A in ESCC." (PMID 34617194, 2022). "Results of qRT-PCR partially demonstrated the bioinformatics results that the mRNA levels of CXCL10, CXCL9, CCL5, and CCR2 were remarkably elevated in tumor tissues collected from PTC patients coexistent with HT than those without HT (P < 0.001)." (PMID 36266640, 2022). "LIF blockade results in TAM phenotypic changes, in which C-X-C motif chemokine ligand 9 (CXCL9) expression is elevated, and CD8+ T cells are recruited to the tumor, suggesting that LIF is involved in resistance to immune checkpoint blockade." (PMID 35740622, 2022). "The expression of cytokines, such as CXCL9, CXCL10, CXCL11 and CXCL13, that attract specific immune cells at the tumor site was significantly higher in HBV and HCV tumors than in non-B, non-C tumors." (PMID 36557005, 2022). "CXCL9 and CXCL10 are chemokine ligands of CXCR3, which differ from other chemokines due to their ability to restrain tumor growth and enhance antitumor immunity." (PMID 35320940, 2022). "Recent studies have revealed that ARID1A loss impairs the expression of IFN signaling components, especially Th1-type chemokines (CXCL9 and CXCL10), to compromise effector T-cell tumor trafficking and antitumor immunity." (PMID 36435834, 2022). "The presence of Batf3 DCs, CXCL9 and CXCL10 in the tumor microenvironment independently correlated with T cell infiltration." (PMID 35626062, 2022).